KIF18B (kinesin family member 18B)
Description:
In complex with KIF2C, constitutes the major microtubule plus-end depolymerizing activity in mitotic cells. Its major role may be to transport KIF2C and/or MAPRE1 along microtubules.
Tractability: PROTAC: ubiquitination databases record sites on it.
Target class: Other cytosolic protein
Gene: Protein-coding gene on chromosome 17 (44,924,707 to 44,947,776, reverse strand). Ensembl gene ENSG00000186185.
Subcellular location: Nucleus; Cytoplasm; Cytoplasm, cytoskeleton
Subcellular location (Human Protein Atlas): Microtubule ends; Nucleoplasm; Cytosol; Nuclear bodies; Nucleoli
Pathways (Reactome):
Hemostasis: Kinesins
Vesicle-mediated transport: COPI-dependent Golgi-to-ER retrograde traffic
Gene Ontology:
Molecular function: cytoskeletal motor activity; kinesin binding; protein binding; plus-end-directed microtubule motor activity; ATP binding; microtubule binding; microtubule motor activity
Biological process: microtubule depolymerization; mitotic cell cycle; regulation of cell division; mitotic sister chromatid segregation; microtubule-based movement
Cellular component: astral microtubule; cytoplasm; cytosol; microtubule end; microtubule plus-end; nuclear body; nucleolus; nucleoplasm; nucleus; kinesin complex; mitotic spindle astral microtubule; mitotic spindle midzone; cytoskeleton; spindle microtubule
Genetic constraint (gnomAD): Loss-of-function variants: 46 observed, 75.3 expected, observed/expected ratio (o/e) 0.61, 90% interval 0.48 to 0.78. The upper end of that interval is the gene's LOEUF score, 0.78, which puts it in group 3 of 6, group 1 being the genes least tolerant of losing a copy. Missense variants: 991 observed, 1,100.9 expected, observed/expected ratio (o/e) 0.9, 90% interval 0.85 to 0.95. Synonymous variants: 439 observed, 449.82 expected, observed/expected ratio (o/e) 0.98, 90% interval 0.9 to 1.06.
Homologues: Orthologues: chimpanzee KIF18B (98% identical), macaque KIF18B (94% identical), pig KIF18B (80% identical), dog KIF18B (79% identical), rat Kif18b (72% identical), mouse Kif18b (71% identical), tropical clawed frog kif18b (47% identical). Paralogues in human: KIF18A (36% identical), KIF13B (25% identical), KIF1A (25% identical), KIF13A (24% identical), KIF3B (24% identical), KIF1B (24% identical), KIF17 (23% identical), KIF19 (23% identical), KIF3C (22% identical), KIF3A (22% identical), KIF16B (21% identical), KIF1C (21% identical), and 29 more.
Diseases named in the same sentence as KIF18B in open-access papers:
KIF18B is named in the same sentence as 37 diseases in open-access papers, as found by Europe PMC text mining. Sharing a sentence is not in itself a finding about the gene and the disease. The quoted sentences say what the papers report.
cervical cancer (8 papers, 2020 to 2025). A primary or metastatic malignant neoplasm involving the cervix. "In contrast, in hepatocellular carcinoma, cervical cancer, and bladder urothelial carcinoma, the modulation of tumor cell viability by KIF18B is associated with the Wnt/β-catenin pathway." (PMID 40110038, 2025). "KIF18B is shown to activate the Wnt/β‐catenin pathway in cervical cancer, reducing Cyclin D1 expression." (PMID 40405535, 2025). "Only another protein of the kinesin superfamily (KIF18B) was correlated with β-catenin in cervical cancer and was suggested to act in breast cancer by activating the Wnt/β-catenin signaling pathway." (PMID 38195458, 2024). "In cervical cancer, it was found that KIF18B acts as an oncogene that promotes cervical carcinogenesis by activating the Wnt/β-catenin signaling pathway." (PMID 38195458, 2024). "KIF18B gene knockout induces cell cycle arrest and inhibits proliferation, migration, and invasion of cervical cancer cells." (PMID 32587775, 2020). "Conversely, overexpression of KIF18B promotes proliferation, migration, and invasion of cervical cancer cells." (PMID 32587775, 2020). "KIF18B has been shown to activate the Wnt/β-catenin signaling pathway in cervical cancer cells." (PMID 32587775, 2020). "KIF18B was rarely reported with MPM, but it was reported promoting tumor progression in cervical cancer, hepatocellular carcinoma, and pancreatic cancer." (PMID 32849853, 2020).
hepatocellular carcinoma (8 papers, 2015 to 2025). A malignant tumor that arises from hepatocytes. "Another research reveals that KIF18B is down-regulated in senescent cells and abnormally up-regulated in hepatocellular carcinoma cells, and the overexpression of KIF18B was a risk factor for poorer survival." (PMID 32973873, 2020). "For example, KIF15 can promote cancer stem cell phenotype in hepatocellular carcinoma, while KIF18B can promote cell proliferation in hepatocellular carcinoma." (PMID 35524313, 2022). "Recent research reported that KIF18B promotes hepatocellular carcinoma progression through activating the Wnt/β-catenin-signaling pathway, but the upstream regulators of KIF18B are unknown." (PMID 33274225, 2020).
breast carcinoma (7 papers, 2017 to 2024). "Kinesins have been recently highlighted as prognostic biomarkers in breast cancer and a 6-KIFs-based risk score (including four MT-Rel genes, KIF4A, KIF15, KIF18B, KIF20A) was reported to accurately predict outcomes." (PMID 37835564, 2023). "Previous studies have reported that KIF18B knockdown may increase the sensitivity of colon and breast cancer cells to oxaliplatin and doxorubicin, respectively." (PMID 37744335, 2023). "Additionally, KIF18B participates in the Wnt/beta-catenin signaling pathway that induces cell proliferation, migration, and invasion in cervical and breast cancers." (PMID 36499051, 2022). "For example, Ispinesib, a KIF11 inhibitor, was evaluated in a phase I clinical trial in breast cancer, although the specific inhibitors for KIF4A and KIF18B are still limited." (PMID 36499051, 2022).
prostate carcinoma (7 papers, 2021 to 2025). A carcinoma that arises from epithelial cells of the prostate gland. "We also identified an association between high KIF18B expression and poor prostate cancer-free survival based on data from TCGA, and with poor biochemical recurrence-free survival based on clinicopathological data from patients seen at our center." (PMID 33753726, 2021). "Moreover, Kaplan–Meier survival analyses demonstrated that high KIF18B expression was significantly associated with poorer prostate cancer-free survival." (PMID 33753726, 2021). "In a study involving human prostate cancer cells, KIF18B was shown to promote prostate cancer progression by activating mTOR signaling pathway." (PMID 37957153, 2023). "circKIF18B_003 was derived from oncogene KIF18B and was markedly overexpressed in prostate cancer tissues." (PMID 38049827, 2023). "We speculated that oncoprotein KIF18B-derived circRNA circKIF18B_003 might have roles in prostate cancer promotion." (PMID 38049827, 2023). "KIF18B, as an oncogene, plays a vital role in prostate cancer progression." (PMID 38049827, 2023). "SOX11, CRISP3, KIF18B, and MELK expression levels have also been found to be positively correlated with poor prostate cancer patient prognostic outcomes, while ZNF556 has been associated with poor colon cancer patient prognosis." (PMID 36245556, 2022). "Expression of kinesin family member 18B (KIF18B), an ATPase with key roles in cell division, is deregulated in many cancers, but its involvement in prostate cancer (PCa) is unclear." (PMID 33753726, 2021). "Furthermore, relative to the non-castration-resistant prostate cancer cell line (LNCaP), the expression of KIF14, CENPE, KIF15, KIF18B, and KIFC1 was significantly elevated in the castration-resistant PCa cell line (DU145)." (PMID 40956849, 2025).
lung adenocarcinoma (5 papers, 2020 to 2026). A carcinoma that arises from the lung and is characterized by the presence of malignant glandular epithelial cells. "High levels of KIF18B were associated with poor prognosis in lung adenocarcinoma patients." (PMID 32849853, 2020). "Study has indicated that a poor prognosis was related to the patients with a high KIF20A expression in bladder cancer and a high KIF18B expression in lung adenocarcinoma." (PMID 34112092, 2021). "Moreover, microtubule-regulating kinesins, such as KIF18B, are involved in accelerating cell proliferation, migration, and invasion via mediating AKT/mTOR, and thereby contribute to advanced tumor stage and correlates with unfavorable prognosis in lung adenocarcinoma patients." (PMID 32631334, 2020).
lung carcinoma (5 papers, 2020 to 2025). "In prostate, breast, and lung cancers, the proliferative regulation of tumor cells by KIF18B is contingent upon the activation of the AKT pathway." (PMID 40110038, 2025). "The present study identified and validated NUF2, KIF4A, KIF18B, DLGAP5, NEK2, and LRRK2 as promising diagnostic biomarkers for lung cancer." (PMID 36499051, 2022). "Numerous studies have correlated KIF18B with the proliferation, migration and invasion of cancer cells, whereas KIF14 has been implicated in the development of gastric, colorectal and lung cancers." (PMID 38494845, 2024). "Previous evidence showed that KIF18B was positively correlated with CD8+ T cells in renal clear cell carcinoma and lung carcinoma." (PMID 37744335, 2023). "For the first time, we propose NUF2, KIF4A, KIF18B, DLGAP5, NEK2, and LRRK2 as biomarkers for lung cancer progression." (PMID 36499051, 2022). "Here, NUF2, KIF4A, and KIF18B were commonly upregulated, and LRRK2 was commonly downregulated in both lung cancer subtypes." (PMID 36499051, 2022). "In cases of lung cancer, KIF4A was reported to promote cell proliferation and migration and inhibit apoptosis in LUAD cell lines, whereas KIF18B was suggested to promote LUAD cell proliferation, migration, and invasion via the Rac1/Akt/mammalian target of rapamycin (mTOR) signaling pathway." (PMID 36499051, 2022).
osteosarcoma (4 papers, 2020 to 2026). A usually aggressive malignant bone-forming mesenchymal neoplasm, predominantly affecting adolescents and young adults. "Previous studies have reported the overexpression of KIF11, KIF15, and KIF18B in various malignancies, including gallbladder cancer, oral cancer, meningioma, pancreatic cancer, and osteosarcoma, supporting our findings." (PMID 37711200, 2023). "The results of immunohistochemical staining for KIF18B and Ki67 of cancer tissue and adjacent tissue of osteosarcoma patients were analyzed, reveled higher expression of Ki67 and KIF18B in tissue of osteosarcoma compared to that of adjacent tissue." (PMID 32587775, 2020). "Knockdown of KIF18B induced G1/S phase arrest and significantly inhibited proliferation, migration, and invasion of osteosarcoma cells, both in vitro and in vivo." (PMID 32587775, 2020). "KIF18B is overexpressed in osteosarcoma cells and tissues and its expression is positively correlated with the degree of malignancy of U2OS cells." (PMID 32587775, 2020). "Protein and mRNA levels of KIF18B were additionally upregulated in the osteosarcoma cell lines HOS, U2OS, and Saos-2." (PMID 32587775, 2020). "While KIF18B overexpression in osteosarcoma tissue is clearly detected, its specific function in the disease process remains to be established." (PMID 32587775, 2020). "Further qRT-PCR analysis of KIF18B in 20 paired osteosarcoma tissue samples (tumor and adjacent normal tissues) revealed overexpression in malignant tissue in 75% (15/20) cases (P < 0.001)." (PMID 32587775, 2020). "Consistently, KIF18B protein was overexpressed in all three osteosarcoma cell lines, in particular, HOS and U2OS." (PMID 32587775, 2020). "In osteosarcoma specimens, qPCR analysis showed positive co-expression of β-catenin with KIF18B and ATF2 relative to that in adjacent tissues." (PMID 32587775, 2020). "We additionally evaluated the effects of KIF18B on proliferation, migration, and invasion of osteosarcoma cells, both in vitro and in vivo." (PMID 32587775, 2020). "Data from the present study suggest that KIF18B is a potential oncogene that promotes osteosarcoma cell proliferation and migration, both in vitro and in vivo." (PMID 32587775, 2020). "Downregulation of KIF18B leads to arrest of U2OS osteosarcoma cells in the G1/S phase, resulting in decreased proliferation, migration, and invasion." (PMID 32587775, 2020). "Our collective findings support the potential utility of KIF18B as a novel prognostic biomarker for osteosarcoma." (PMID 32587775, 2020). "Experiments by our group showed KIF18B overexpression in osteosarcoma tissue, but its specific function in the disease process is currently unclear." (PMID 32587775, 2020). "Tumor sizes in the shKIF18B group were significantly lower relative to that in the control group, suggesting that expression of KIF18B may be positively correlated with degree of osteosarcoma malignancy." (PMID 32587775, 2020). "KIF18B mRNA expression was 2–3 times higher in osteosarcoma cells than hFOB1.19 cells." (PMID 32587775, 2020). "Accordingly, we speculated that KIF18B may affect the tumorigenicity of osteosarcoma cells by influencing the Wnt signaling pathway." (PMID 32587775, 2020). "KIF18B regulated β-catenin expression at the transcriptional level by controlling nuclear aggregation of ATF2 and at the post-transcriptional level by interacting with the adenomatous polyposis coli (APC) tumor suppressor gene in osteosarcoma cells." (PMID 32587775, 2020).
bladder urothelial carcinoma (3 papers, 2023 to 2025). "In urothelial carcinoma of the bladder, the axis of miR-139-3p/KIF18B/Wnt/β-catenin was demonstrated to be an effective therapeutic target by inhibiting the malignant progression of the tumor." (PMID 40662137, 2025). "In contrast, KIF18B demonstrated a significant negative correlation with Tregs in skin cutaneous melanoma (R = -0.19), lymphoid neoplasm diffuse large B-cell lymphoma (R = -0.51), and bladder urothelial carcinoma (R = -0.26)." (PMID 37744335, 2023).
Clear Cell Renal Cell Carcinoma (3 papers, 2020 to 2024). "It has been reported that KIF20B promoted the progression of clear cell renal cell carcinoma, and KIF18B promotes cell proliferation in colon adenocarcinoma." (PMID 38713252, 2024). "Similarly, in prostate adenocarcinoma and renal clear cell carcinoma, highly expressed KIF18B exhibited a significant positive correlation with Tregs, albeit with relatively low correlation coefficients of 0.18 and 0.29, respectively." (PMID 37744335, 2023).
colorectal cancer (3 papers, 2020 to 2025). A primary or metastatic malignant neoplasm that affects the colon or rectum. "In colorectal cancer, KIF18B has been observed to interact with SP1, resulting in the upregulation of PARPBP and the maintenance of oxaliplatin resistance in oxaliplatin-resistant colorectal cancer (OR-CRC) cells." (PMID 40110038, 2025). "KIF14, KIF18B, KIF23, KIF4A, KNTC1, NCAPG2, and MCM3 regulate chromosomal integrity, mitotic spindle formation, and DNA replication, processes that are frequently dysregulated in colorectal cancer." (PMID 40405535, 2025).
melanoma (3 papers, 2019 to 2025). A malignant, usually aggressive tumor composed of atypical, neoplastic melanocytes. "Mice were vaccinated prophylactically with p30 peptide encoding B16 melanoma neoantigen (K739N mutation in Kif18b gene)." (PMID 40650228, 2025). "This pDNA was a mix of four different plasmids globally encoding three melanoma neoantigens, specifically designed in silico according to the B16F1 mutations (Kif18b, Cpsf3l and Pbk), and two TAAs (TRP2 and gp100)." (PMID 31291991, 2019). "The neoantigens Kif18b and Pbk presented the same mutations described in the literature for B16F10 melanoma, while the Cpsf3l neoantigen sequence that we found in B16F1 cells was different." (PMID 31291991, 2019).
pancreatic cancer (3 papers, 2020 to 2023). "Previous studies have shown that KIF18B promotes pancreatic cancer cell proliferation by activating CDCA8 in in vitro assays." (PMID 36358852, 2022).
sarcoma (3 papers, 2020 to 2025). A usually aggressive malignant neoplasm of the soft tissue or bone. "In some sarcomas, KIF18b is increased after IR exposure facilitating their radioresistance to clinical therapies." (PMID 36362070, 2022). "Differential mRNA and protein expression of KIF18B in immortalized human osteoblasts, hFOB1.19, and three sarcoma cell lines, HOS, U2OS, and Saos-2, was detected with qRT-PCR and Western blot, respectively." (PMID 32587775, 2020). "By contrast, KIF18B-silenced sarcoma cells seem to be more sensitive to IR." (PMID 36362070, 2022).
glioblastoma multiforme (2 papers, 2015 to 2025). "Nevertheless, the expression profile, prognostic relevance, and biological functions of KIF18B in glioblastoma multiforme (GBM) have not been comprehensively investigated." (PMID 40110038, 2025).